STAG2 (STAG2 cohesin complex component)
Diseases named in the same sentence as STAG2 in open-access papers (continued):
Sharing a sentence is not in itself a finding about the gene and the disease.
cancer (continued). "In this study, we used CRIPSR-Cas9 whole-genome screening to investigate potential genetic interactions of STAG2, a member of the cohesin complex that has a high rate of loss in certain types of cancer." (PMID 34462321, 2021). "These include connecting cancers with HRD or STAG2 deficiency with PARP inhibitors, epigenetic dysregulation with histone deacetylase or EZH2 inhibitors, and DNA checkpoint abnormalities with ATM or ATR inhibitors, to name a few." (PMID 34101093, 2021). "Based on our screen results and those of others, it seems unlikely that a “loss-of-function” therapeutic target beyond STAG1 will be discovered that will work in all diverse cancer types with STAG2 loss." (PMID 34462321, 2021). "STAG2 is the most frequently mutated subunit and is one of 12 genes to be mutated in four or more cancers." (PMID 34202641, 2021). "The recurrent, deleterious, and likely truncal nature of STAG2 mutations strongly suggests that STAG2 loss-of-function alterations represent cancer driver events." (PMID 32467316, 2020). "Discovery of highly prevalent STAG2 mutations has been an unexpected finding emerging from large-scale cancer genome studies over the last decade that opens up possibilities for the development of new therapeutic strategies and targets." (PMID 32467316, 2020). "Of the cohesin genes, STAG2 is the most frequently mutated, with about half of cohesin mutations in cancer involving STAG2." (PMID 33284104, 2020). "STAG1 inhibition in cancer cells with STAG2 mutation causes chromosome segregation defects and subsequent lethality." (PMID 33284104, 2020). "STAG2 is significantly mutated in four or more human cancer types and experimental data indicates that STAG2 gain-of-function changes cause loss of sister chromatid cohesion and CIN." (PMID 30823889, 2019). "Instead, somatic mutations in the NIPBL, RAD21, SMC1A, SMC3 and STAG2 genes have been described in many human cancers including acute myeloid leukemia, bladder, and colorectal cancer." (PMID 30823889, 2019). "Genomic analyses have identified that the cohesin subunit STAG2 is frequently inactivated by mutations in cancer." (PMID 30975996, 2019). "STAG2 has been identified as one of only 12 genes that are significantly mutated in four or more human cancer types by The Cancer Genome Atlas30, in which STAG2 mutation defines molecular subgroups of these tumor types with distinct clinical outcomes." (PMID 30975996, 2019). "To further confirm the differential sensitivity of STAG2-proficient versus deficient cancer cells to DNA damaging chemotherapeutic agents, we performed clonogenic survival assays with the DNA alkylating agent cyclophosphamide." (PMID 30975996, 2019). "Here we show that cohesin has critical functions at the DNA replication fork regulated by STAG2, and that the replication fork instability caused by STAG2 inactivation creates a targetable synthetic lethality in cohesin-mutant cancers." (PMID 30975996, 2019). "To prove that the synthetic lethality between STAG1 and STAG2 is context independent, we have tested their genetic interaction in several cancer cell lines where the two genes have variable mutational and copy number status." (PMID 28430577, 2017). "About half a million cancer patients worldwide have tumors that feature mutations to the gene that produces a protein called STAG2, a component of a large protein ring called cohesin." (PMID 28691904, 2017). "Such vulnerabilities hold the promise for the development of selective treatments for patients suffering from STAG2 mutated cancer." (PMID 28691904, 2017). "STAG1 represents a vulnerability of cancer cells carrying mutations in the major emerging tumor suppressor STAG2 across different cancer contexts." (PMID 28691904, 2017). "For example, loss of function mutations in STAG2, which encodes the cohesin protein complex subunit SA-2, has been found in cancer cell lines and in primary tumors." (PMID 28445142, 2017).
cancer (continued). "We inhibited STAG1 and STAG2 in several cancer cell lines where the two genes have variable mutation and copy number status." (PMID 28430577, 2017). "LoF alterations are clearly associated with a significant reduction of STAG2 expression in cancer cell lines and in TCGA samples, supporting a reduced gene activity after somatic inactivation." (PMID 28430577, 2017). "We next expanded our analysis to patient-derived STAG2 mutations and STAG2-mutant cancer cell lines in order to investigate the disease relevance of the observed synthetic lethality." (PMID 28691904, 2017). "Here we analyze the effect of cancer-causing mutations in STAG2 on its ability regulate the separation of chromosomes during cell division." (PMID 26871722, 2016). "In an initial attempt to do this, we created several STAG2 expressing lentiviruses for reconstituting wild-type and mutant STAG2 expression in cancer cells harboring STAG2 mutations." (PMID 26871722, 2016). "In our initial studies identifying STAG2 mutations in cancer, we demonstrated using isogenic human cultured cell systems that STAG2 mutations can lead to alterations of chromosome counts and aneuploidy." (PMID 26871722, 2016). "In fact, STAG2 is one of only 12 genes known to be significantly mutated in four of more types of cancer." (PMID 26871722, 2016). "We find that this cancer is frequently affected by mutations in STAG2, a gene that has recently gained attention due to its importance in the biology of several cancer types." (PMID 25010205, 2014). "Given the significant percentage of tumors harboring a STAG2 mutation in this cancer type, further investigation into the oncogenic mechanism, clinical consequence, as well as strategies for directed therapy are warranted." (PMID 25010205, 2014). "Further, loss of STAG2 protein was observed in several human cancer cell lines, primary tumors and xenografts of different origin." (PMID 24088605, 2013). "To date, several studies have identified vulnerabilities of STAG2 deficient or mutant cancer cells." (PMID 40025053, 2025). "(STAG2 is a subunit of the cohesin complex, and its inactivation can cause aneuploidy in cancer)." (PMID 39962391, 2025). "However, testing the effects of STAG2 inactivation, which is more frequently mutated in cancer, showed more subtle changes in TADs structure." (PMID 39594644, 2024). "Among the cohesin genes, STAG2 is the most frequently mutated in cancer." (PMID 38279279, 2024). "Notably, the study illuminates that Stromal antigen 2 (STAG2) deficient cancer cells manifest heightened sensitivity to ATM inhibition." (PMID 37985839, 2023). "It remains unclear how the mutated STAG2 functions in cancer, elucidation of which might uncover a new therapeutic candidate." (PMID 36589746, 2022). "Stromal Antigen 2 (STAG2) is the most commonly mutated subunit, and in a recent analysis was identified as one of only 12 genes that are significantly mutated in four or more cancer types." (PMID 36016405, 2022). "STAG2, a cohesin family gene, is among the most recurrently mutated genes in cancer." (PMID 36016405, 2022). "In cancer, the STAG2 gene is more highly mutated than any other cohesin component, including STAG1." (PMID 34462321, 2021). "STAG2 is one of only twelve genes known to be mutated in more than four major human cancer types." (PMID 32065581, 2020). "As STAG2 is the most abundant and most mutated cohesin gene in human cancers we performed a microarray gene expression analysis, comparing gene expression in MCF-7 cells post STAG2KD with untreated cells (unt) and with cells treated with non-targeting siRNA (non-T)." (PMID 32629605, 2020). "The reason why cohesin mutations in human cancers most commonly affect STAG2 and less commonly the other cohesin subunits has been unknown." (PMID 30975996, 2019).
cancer (continued). "Our data also imply that for the other cancers that harbor STAG2 mutations and an intact DNA-sensing mechanism, depending on the type of IFN induction, certain oncolytic viral vectors may also fail to function as expected." (PMID 29662124, 2018). "This knowledge could ultimately be used to develop drugs that would kill off only those cancer cells that have mutations that affect STAG2." (PMID 28691904, 2017). "Furthermore, expression analysis did not reveal upregulation of STAG1 protein or mRNA as a major compensatory mechanism for the loss of STAG2 function in cancer cell lines or patient tumors." (PMID 28691904, 2017). "Both STAG1 and STAG2 acquire somatic LoF alterations (homozygous gene deletions, truncating mutations and multiple hits) as well as putative damaging missense and splicing mutations in a variety of human cancers of The Cancer Genome Atlas (TCGA)." (PMID 28430577, 2017). "When taken together with the results presented for the missense mutations tested, these results further call into question whether the cancer relevant phenotypes of STAG2 mutations are directly related to cohesion and aneuploidy." (PMID 26871722, 2016). "Mutations of the STAG2 gene are common in several types of adult and pediatric cancers." (PMID 26871722, 2016). "We then tested an alternate hypothesis—that STAG2 mutations cause alterations in the amount and/or subunit composition of cohesin in human cancer cells." (PMID 26871722, 2016). "In addition to the frequent mutations in human tumors, the role of STAG2 inactivation in cancer pathogenesis is also highlighted by the fact that it is commonly altered in transposon-mediated tumorigenesis in mouse model systems." (PMID 26871722, 2016). "Inactivating mutations of STAG2 have been reported at low frequency in several cancers." (PMID 24270882, 2014). "Somatic mutations in STAG2 have now been reported in a variety of human cancers." (PMID 24484537, 2014). "This represents the highest frequency of STAG2 mutation detected in any cancer to date." (PMID 24270882, 2014). "Hence, targeting STAG1 in STAG2-mutated cancer cells is an attractive therapeutic approach." (PMID 38033389, 2023). "Although it has been reported that a cancer-associated STAG2 mutation can support sister chromatid cohesion but was unable to repress transcription at DSBs; this may be due to stalled replication forks and collapse of the interaction between the cohesin and the replication machinery." (PMID 32883299, 2020). "Thus, STAG1-directed small molecule degraders that engage a suitable human E3 ligase such as VHL or CRBN may provide a promising therapeutic modality for the treatment of STAG2-mutated cancers." (PMID 32467316, 2020). "However, the reason STAG2 mutations are selected during tumorigenesis and strategies for therapeutically targeting mutant cancer cells are largely unknown." (PMID 30975996, 2019). "Treatment with inhibitors of poly ADP-ribose polymerase (PARP), which are used to treat forms of cancer with defects in DNA repair, in combination with STAG2/SA1 depletion resulted in apoptosis in vitro and in vivo." (PMID 41502392, 2026). "Conversely, STAG2, a less commonly mutated gene in CRC yet still previously classed as a cancer driver, seems to act as a passenger, with its frequency in cancer explained by its prevalence in normal tissue alone." (PMID 39920335, 2025). "Using CRISPR-Cas9, we generated isogenic STAG2 wild-type (WT) and knock out (KO) cell lines and treated each cell line with a panel of 312 anti-cancer compounds." (PMID 40025053, 2025). "Given the predicted SMC domain for NIDP2 and considering that STAG2 is frequently mutated in various cancers, we decided to investigate the NIDP2-STAG2 interaction further by IFA of both proteins in TaC12 cells." (PMID 38747635, 2024). "Other cancer-related gene mutations identified by our WES analysis included SATB2, NOTCH3, STAG2 and TET2." (PMID 38201285, 2023).
cancer (continued). "STAG2 is another chromatin regulator that is frequently altered in many human cancers, including UC, in which it acts as a tumor suppressor." (PMID 37079639, 2023). "A number of shared SNVs (53, including PTEN, POLR3D, STAG2) with an average cancer cell fraction of ~1 suggest cluster A as the Most Recent Common Ancestor (MRCA)." (PMID 37628903, 2023). "Careful analysis of Stag2-mutant cancers should shed light on these and deliver new insights into cancers that harbor these mutations." (PMID 37802073, 2023). "Other strategies studied STAG2-mutant specific dependencies in cancer cell lines through different screening approaches." (PMID 38033389, 2023). "Several studies have proved that STAG1 inactivation imparts a potent synthetic lethality in STAG2-mutant cancer cells 49-51." (PMID 35371307, 2022). "Above all, it is apparent that the effects of STAG2 on transcriptional activation and the occurrence of some cancer types." (PMID 36016405, 2022). "Stromal antigen 2 (STAG2), a core subunit of the cohesin complex, is frequently mutated in various cancers." (PMID 35388001, 2022). "Loss of STAG2 results in IRF9 activation, which in turn upregulates PD-L1 expression in cancer cells, suggesting a tumor suppressor function in immune evasion." (PMID 35388001, 2022). "In contrast to the implication of STAG2 in cancer, less information has been reported on the interplay between STAG2 and microorganism infection." (PMID 36016405, 2022). "How exactly changes in chromatin organization mediated by the switch from STAG2- to STAG1-containing cohesin complexes in cohesin-mutant cancer cells lead to DNA replication stress and DNA damage repair defects in cells remain to be elucidated." (PMID 33351783, 2021). "Blocking this interaction was highlighted as another potential avenue for therapeutic targeting of STAG1 in STAG2 mutant cancers." (PMID 34202641, 2021). "Although these results implicate STAG1 as a promising target for selective eradication of STAG2-mutant cancer cells, STAG1 has been shown to be essential for embryonic development, potentially because of gene regulatory functions that remain poorly understood." (PMID 32467316, 2020). "Irrespective of its role in driving tumorigenesis, the abundance of STAG2 alterations in cancer has moved the cohesin subunit into the focus of research for new therapeutic concepts in oncology." (PMID 32467316, 2020). "The cohesin subunit STAG2 has emerged as a recurrently inactivated tumor suppressor in human cancers." (PMID 32467316, 2020). "Together with other recent studies showing enhanced PARP inhibitor sensitivity in cohesin-deficient cells, these studies lay the foundation for clinical trials of targeted agents in STAG2 mutant cancers." (PMID 30975996, 2019). "Herein we have identified an essential role for the STAG2 gene in stability of the replication fork that creates a targetable synthetic lethality in STAG2 mutant cancers." (PMID 30975996, 2019). "Two recent studies have both demonstrated that STAG2 mutant cancer cells have a critical dependence on STAG140,41." (PMID 30975996, 2019). "We provide strong evidence that STAG1 is a promising therapeutic target in cancers with inactivating alterations of STAG2." (PMID 28430577, 2017). "This condition mimics that of cancer samples where STAG2 is somatically inactivated and supports the development of STAG1 as a therapeutic target in these tumours." (PMID 28430577, 2017). "In several cancer types, the somatic inactivation of STAG2 is selected for due to its tumour suppressor role." (PMID 28430577, 2017). "Our data on SK-ES-1 cells, which have inactive STAG2 gene, show that this vulnerability can be exploited to specifically target STAG2-altered cancers by developing specific STAG1 inhibitors." (PMID 28430577, 2017).
cancer (continued). "The estimated half a million individuals with STAG2-mutant malignancies would greatly profit from exploring specific dependencies of these cancers." (PMID 28691904, 2017). "Our results revealed further cancer-relevant target genes including STAG2, CNOT6, SOX2, CDC25A and SFRS3." (PMID 23358700, 2013). "Isoforms with increased proportions in stem/TA-like cells (cancer cells) were linked to worse survival, such as COMT-202, TTC39A-216; while increased proportions in stem/TA-like cells (cancer) indicated better prognosis, such as STAG2-203 and CCND3-203." (PMID 40702779, 2025). "While STAG2 is categorized as a tumor suppressor in many cancer types, its role is tissue specific." (PMID 40025053, 2025). "We chose to focus on STAG2 because of its importance as a tumor-suppressor gene lost in various cancers, PAXIP1 a recently identified cohesin regulator, and the Haspin kinase since it may be targetable with small molecules." (PMID 38478595, 2024). "In addition to STAG2, numerous NIDP2-associated host nuclear proteins implicated in various cancers were identified, shedding light on the potential role of the T. annulata exported protein family NIDP in host cell transformation and cancer-related pathways." (PMID 38747635, 2024). "However, mutations in STAG2, but not STAG1, occur frequently in various cancers, suggesting a unique role of STAG2 in cancer biology." (PMID 35388001, 2022). "The role of STAG2 is likely cell-context dependent, which may explain why in some cancer types it has tumor-suppressive properties, and in others it has oncogenic properties." (PMID 36275363, 2022). "However, the impact of STAG2 inactivation on 3D genome organization, especially the long-range enhancer-promoter contacts and subsequent gene expression control in cancer, remains poorly understood." (PMID 35388001, 2022). "Biological pathway analysis and functional enrichment analysis in this study illustrated that cell division-related processes, tumor vascularization, EMT, and cancer signaling pathways, such as hedgehog signaling, were significantly enriched in the high STAG2 expression group in EAC patients." (PMID 35371307, 2022). "PPI analysis illustrated that STAG2 and RAD21 could cross-talk through cancer-associated modules and performed the core roles of the whole PPI network." (PMID 35371307, 2022). "STAG1 (5%), NIPBL (4.9%), STAG2 (3.4%) and PDS5B (3.4%) are the most frequently mutated in cancer." (PMID 35287703, 2022). "However, cancer cell lines with inactivated STAG2 were genomically stable though they exhibited decreased cell viability and altered cell cycle." (PMID 35287703, 2022). "To determine whether the dependence of STAG2-mutated cells on STAG1 was a generalizable interaction beyond our three paired backgrounds, we examined the AVANA CRISPR Cancer Dependency Map (DepMap) dataset." (PMID 34462321, 2021). "Contaminants included the cancer genes KRAS (2 samples, including one sample identified by manual review), STAG2 (35 samples), DDX58 (25 samples; DDX58 encodes RIG-I), and SNAP25 (9 samples), some of which can be traced to other projects from the same laboratory." (PMID 34952565, 2021). "This affected 17/333 pathway-associated genes including six known cancer genes (HNRNPA2B1, STAG2, TCF7L2, SUZ12, CLTC, and ZNF521), Thus, the integration procedure prioritized specific pathway-related genes compared to their original rankings in individual mutation datasets." (PMID 32024846, 2020). "While our analysis could indicate conserved upregulation of the Wnt pathway in STAG2 mutant cancers, a caveat is that the true situation is likely to be more complex." (PMID 33284104, 2020).